TRIM6 (tripartite motif containing 6)
Diseases named in the same sentence as TRIM6 in open-access papers (continued):
Sharing a sentence is not in itself a finding about the gene and the disease.
cancer (10 papers, 2020 to 2025). A tumor composed of atypical neoplastic, often pleomorphic cells that invade other tissues. "We also analyzed the differential expression of Sox4, E2f1, Trpv4 and Trim6, which are the genes important for cancer stem cell behavior and function." (PMID 40568073, 2025). "TRIM6 has been reported to increase cell proliferation, invasion, metastasis, and angiogenesis in cancer." (PMID 38912065, 2024). "The 3-year cancer-specific survival rate of patients with low-TRIM6 expression was 58.0%, while it decreased to 43.0% in those with high-TRIM6 expression." (PMID 38813007, 2023). "It was noted that higher TRIM6 protein expression in tumor tissues is correlated with worse cancer-specific survival of HCC patients (p = 0.002)." (PMID 38813007, 2023). "To investigate the expression level of TRIM6 in tumor and normal tissue, we analyzed TRIM6 mRNA expression in various cancers and normal tissues using data from the TCGA and GTEx databases." (PMID 37759698, 2023). "TRIM6 mRNA level was elevated in cancer samples compared to that of adjacent mucosa samples (paired student’s t-test, P < 0.01)." (PMID 31992359, 2020). "TRIM6 is highly expressed in various cancers and exerts oncogenic functions." (PMID 40961099, 2025). "Furthermore, patients with higher TRIM6 level were characterized both with worse overall survival and worse cancer-specific survival." (PMID 38813007, 2023). "We also investigated how TRIM6 regulated SLC1A5 in H460 cancer cells." (PMID 36654781, 2023). "Interestingly, TRIM6 expression was positively correlated with several cancer-related pathways, including NF-κB, CTNNB1, and STAT3 signaling." (PMID 34589421, 2021). "Collectively, these data indicate that TRIM6 expression levels influence the anti-cancer efficacy of different drugs, which may be taken into account before these drugs were applied to CRC patients." (PMID 31992359, 2020). "This miRNA promotes cell proliferation and invasion by targeting RAB14.These findings suggest that the TRIM6-related miRNAs identified in this study may not only play functional roles in AML but also warrant further investigation in the context of other cancer types." (PMID 40961099, 2025). "However, TRIM6 and TRIM34 individually encode ubiquitin ligases that may play roles in cancer and placenta development." (PMID 38912065, 2024). "However, the potential involvement of TRIM6 in cancer development has received little attention." (PMID 37759698, 2023). "However, the role of TRIM6 in the development of cancer has rarely been reported." (PMID 37759698, 2023). "Besides, we found that TRIM6 mRNA expressions in H460 and PC9 cells were higher than those in other cancer cell lines; therefore, we selected these two cell lines in our further study." (PMID 36654781, 2023). "Furthermore, the cell line with a lower TRIM6 expression (SW620) was metastatic, indicating the complicated regulation of cancer cell metastasis." (PMID 34589421, 2021).
tumor (10 papers, 2009 to 2025). "The “CIBERSORT” analysis indicated a significant correlation between TRIM6 expression and tumor-infiltrating immune cells." (PMID 40961099, 2025). "The results showed that TRIM6 expression was significantly reduced in tumor samples compared to control samples." (PMID 40961099, 2025). "In future studies, we plan to establish xenograft mouse models to observe the effects of TRIM6 overexpression on tumor growth and disease progression, thereby enabling a more comprehensive evaluation of the therapeutic potential of TRIM6 in the context of AML." (PMID 40961099, 2025). "In contrast, in AML studied here, TRIM6 exhibits potential tumor-suppressive effects, with its downregulation closely associated with poor prognosis." (PMID 40961099, 2025). "The relationship between TRIM6 expression and tumor immune cell infiltration was analyzed using data from the TCGA dataset." (PMID 40961099, 2025). "Meanwhile, Trim6; cGAS dKO cells substantially abrogated the tumor growth suppressive effect observed in Trim6 KO cells when MTC and B16F10 cells were transplanted into C57BL/6J mice." (PMID 40817248, 2025). "Depletion of TRIM6 retarded the tumor growth of MTC cells in immunocompetent C57BL/6J mice, whereas this suppression was compromised in nude mice." (PMID 40817248, 2025). "Yet, recent studies revealed some additional actions of TRIM6, including the regulation on tumor progression." (PMID 36654781, 2023). "The role of TRIM6 on ferroptosis and chemosensitivity was further tested in mouse tumor xenograft models." (PMID 36654781, 2023). "Despite TRIM6 having been reported to be involved malignancies, its detailed function seems distinct in different tumor types." (PMID 38813007, 2023). "Chi-square test revealed that tumors with larger tumor size exhibited higher TRIM6 level (p = 0.041)." (PMID 38813007, 2023). "Consistently, TCGA dataset showed a significantly higher mRNA level of TRIM6 in HCC tumor tissues than that in normal liver tissues (p < 0.001)." (PMID 38813007, 2023). "Higher TRIM6 expression was correlated with larger tumor size, later tumor stage, and worse prognosis." (PMID 38813007, 2023). "Based on statistical analyses, we found that expression level of TRIM6 was positively correlated with HCC tumor size and TNM stage." (PMID 38813007, 2023). "Considering the clinical significance of TRIM6, we were engaged to further explore its detailed tumor-related functions in HCC." (PMID 38813007, 2023). "By exploring the relationship between TRIM6 expression and tumor immune response, our study provides valuable insights into this area of research." (PMID 37759698, 2023). "From the 70 collected samples, Fisher’s exact test showed that the TRIM6 levels were correlated with the tumor size, clinical stage, and metastasis." (PMID 34589421, 2021). "Knocking down of TRIM6 expression in HCT-8 cells (shTRIM6–1) significantly suppressed tumor growth compared with the control cells (shNC)." (PMID 31992359, 2020). "Taken together, these results indicate that TRIM6 knockdown suppressed xenograft tumor growth of CRC cells." (PMID 31992359, 2020). "However, this study has some limitations, including the lack of in vivo validation, a relatively small clinical validation cohort, and an incomplete understanding of how TRIM6 mediates tumor–immune microenvironment interactions." (PMID 40961099, 2025). "TRIM6-knockout murine models and subcutaneous tumors were subjected to flow cytometry, RNA sequencing, immunoblotting, and ubiquitination assays to characterize tumor-infiltrating lymphocytes (TILs), pathway activation, and TRIM6-mediated regulation of the cGAS-STING axis." (PMID 40817248, 2025). "In conclusion, TRIM6 may function as a tumor-suppressive factor in AML and holds significant prognostic value." (PMID 40961099, 2025). "Consistent with this speculation, blocking CD8+ T cells with an anti-CD8 antibody significantly reversed the inhibition of tumor growth in the Trim6 KO MTC model." (PMID 40817248, 2025).
tumor (continued). "As a result, TRIM6 has a significant correlation with B cell infiltration, implying that TRIM6 may participate in tumor immunology response." (PMID 38813007, 2023). "Furthermore, TRIM6 exhibited a better prognostic predictive role in combination with other conventional prognostic factors such as tumor stage, differentiation grade, serum AFP level, etc.." (PMID 38813007, 2023). "From this aspect, identifying the dysregulated expression of TRIM6 may be more valuable for tumor patients combined with immune diseases." (PMID 38813007, 2023). "In this perspective, TRIM6 stimulates the EMT and production of MMP2, which could facilitate tumor cell migration, invasion, and metastasis, thus, causes tumor recurrence." (PMID 34589421, 2021). "Fisher’s exact test was used to analyze the correlation between TRIM6 protein levels and pathological characteristics, and we found that TRIM6 levels were markedly correlated with tumor size, clinical stage, vital status and carcinoembryonic antigen (CEA) level." (PMID 31992359, 2020). "Several genes are contained within this interval that might be involved in brain development and/or tumor suppression, including TRIM3 and a cluster of genes encoding the more distantly related TRIM5, TRIM6, TRIM22, and TRIM34 genes." (PMID 19250537, 2009). "Finally, we investigated the relationship between TRIM6 and tumor-infiltrating lymphocytes (TILs)." (PMID 37759698, 2023). "Considering that the expression of TRIM6 was significant associated with tumor size, we examined the effect of TRIM6 on cell growth by CCK-8 and BrdU assays, and the results demonstrated that downregulation of TRIM6 remarkably decreased cell proliferation in both HCT-8 and HCT116 cells." (PMID 31992359, 2020). "Strikingly, Trim6 deletion activated the cGAS-STING pathway and simultaneously inhibited tumor progression in MSS malignancies." (PMID 40817248, 2025). "We also examined the role of TRIM6 on DDP- and PTX-mediated tumor-killing actions in mouse xenograft tumor models." (PMID 36654781, 2023). "Therefore, TRIM6 does not exhibit a singular function across tumor types but displays a context-dependent dual role." (PMID 40961099, 2025). "This includes not only serum and immune biomarkers but also tumor-intrinsic biomarkers of immune competence, such as the expression of proteins that regulate key pathways, like cGAS-STING (e.g., RECQL4, TRIM6), which may stratify patients who are likely to need additional innate immune agonists." (PMID 41295487, 2025).
infection (4 papers, 2016 to 2023). The state of being infected such as from the introduction of a foreign agent such as serum, vaccine, antigenic substance or organism. "In contrast, the increased Gln uptake in TRIM6-deficient cells was significantly inhibited by SLC1A5-KD infection." (PMID 36654781, 2023). "Similar results were observed during infection of primary bone marrow-derived dendritic cells (BMDCs) from newly generated Trim6-/- mice." (PMID 35533195, 2022). "We then measured viral titer later during infection in supernatants from wt or Trim6-/- BMDCs infected with either the wt or K309R virus." (PMID 35533195, 2022). "Trim6, Trim56, and Herc6 can also potentiate antiviral immunity by targeting other antiviral effectors in the infection of vesicular stomatitis virus (VSV), pestivirus, and influenza A virus, respectively." (PMID 31057555, 2019). "Taken together, our data shows that NiV matrix protein inhibits IFN responses by targeting the E3-ubiquitin ligase TRIM6 during infection or ectopic expression in cell lines and primary innate immune cells." (PMID 27622505, 2016). "To validate these observations in the context of live Nipah virus infections, we generated recombinant NiV (rNiV) lacking the M protein (rNiV-ΔM) and compared the levels of endogenous TRIM6 during rNiV-WT and rNiV-ΔM infections." (PMID 27622505, 2016). "Infection studies in T6-KO A549s, MEFs, and BMDCs demonstrate that the wt virus is attenuated when TRIM6 is absent, but the mutants’ replication is not affected further." (PMID 35533195, 2022). "The immunoprecipitation of endogenous TRIM6 with L and VP35 supports that these factors may interact during infection to promote the polymerase’s transcriptase activity." (PMID 35533195, 2022).
TRIM6 also shares sentences with these, for which no sentence is quoted: acute myeloid leukemia (1 paper); autoimmune thyroid disease (1); colon cancer (1); Hepatitis (1); immune diseases (1); kidney diseases (1); measles (1); spinal cord tumors (1); systemic lupus erythematosus (1).